RNVU1-33 (RNA, variant U1 small nuclear 33)
Synonyms: U1A5; RNU1-87P
Gene: Small nuclear RNA gene on chromosome 6 (37,915,573 to 37,915,742, forward strand). Ensembl gene ENSG00000200597.
Gene Ontology:
Molecular function: pre-mRNA 5'-splice site binding
Biological process: mRNA 5'-splice site recognition
Cellular component: U1 snRNP
Homologues: Orthologues: chimpanzee U1 (99% identical), macaque U1 (89% identical), rat U1 (56% identical). Paralogues in human: RNVU1-31 (72% identical), RNVU1-28 (72% identical), RNU1-1 (71% identical), RNU1-2 (71% identical), RNU1-27P (71% identical), RNU1-28P (71% identical), RNU1-3 (71% identical), RNU1-4 (71% identical), RNVU1-18 (71% identical), RNVU1-29 (71% identical), U1 (71% identical), RNU1-67P (71% identical), and 134 more.